RN7SKP67 (RN7SK pseudogene 67)
Gene: Miscellaneous RNA gene on chromosome 4 (182,631,454 to 182,631,688, reverse strand). Ensembl gene ENSG00000251714.
Homologues: Orthologues: chimpanzee 7SK (98% identical), guinea pig 7SK (49% identical). Paralogues in human: RN7SKP171 (60% identical), RN7SKP22 (60% identical), RN7SKP239 (59% identical), RN7SKP255 (59% identical), RN7SKP107 (59% identical), RN7SKP71 (59% identical), RN7SKP249 (58% identical), RN7SKP128 (58% identical), RN7SKP193 (58% identical), RN7SKP69 (58% identical), RN7SKP79 (58% identical), RN7SKP90 (58% identical), and 284 more.